MIR593 (microRNA 593)
Synonyms: hsa-mir-593; MIRN593
Gene: MicroRNA gene on chromosome 7 (128,081,861 to 128,081,960, forward strand). Ensembl gene ENSG00000207588.
Gene Ontology:
Biological process: miRNA-mediated post-transcriptional gene silencing
Cellular component: RISC complex